IL10 (interleukin 10)
Diseases named in the same sentence as IL10 in open-access papers (continued):
Sharing a sentence is not in itself a finding about the gene and the disease.
uveitis (continued). "When comparing monophasic uveitis to recurrent uveitis aqueous humor cytokine profiles in humans, intraocular IL10 increased during the remission of monophasic uveitis, and not in recurrent uveitis." (PMID 35980983, 2022). "Other studies using AAV2 to deliver IL10 gene therapy to the eye for experimental uveitis have demonstrated success in reducing posterior uveitis models." (PMID 35980983, 2022). "IL-6 and IL-10 are the most extensively studied cytokines in vitreoretinal lymphomas; studies have demonstrated that elevated aqueous humor or vitreous fluid IL-10 and IL-10/IL-6 ratio can help distinguish vitreoretinal lymphomas from uveitis." (PMID 36059608, 2022). "Mice treated with IL-35 containing exosomes (i35-Exosomes) were protected from developing severe uveitis and disease protection correlated with expansion of IL-10 and IL-35 secreting Treg cells with concomitant suppression of Th17 responses." (PMID 33995347, 2021). "In the case of PVRL, this led to the suggestion for screening of suspected uveitis cases by evaluating IL-10 values and IL-10/IL-6 ratio before vitreous biopsy." (PMID 33146828, 2021). "The intraocular concentration of IL-10 is very useful for etiology diagnosis of uveitis, especially in intraocular lymphoma (IOL)." (PMID 33933004, 2021). "(i) Regulatory B cell (Breg) therapy: Breg immunotherapy with as few as 5x106 cells is sufficient to suppress uveitis by inhibiting Th17/Th1 lymphocytes and converting conventional lymphocytes into IL-10 and/or IL-35-producing regulatory cells." (PMID 33995347, 2021). "In this study, we found that severe uveitis in the CD19-STAT3KO mouse correlated with marked reduction of IL-10-producing Tregs and Bregs, as well as, IL-35-producing Tregs and Bregs." (PMID 33004854, 2020). "We next show an inflammatory cytokine profile from PBMCs cultured from uveitis patients that has significantly elevated IL-12 and IL-23 compared to controls, and significantly lower IL-10 compared to controls." (PMID 31729418, 2019). "For example, in a mouse model of uveitis, distinct doses of IL-10 showed contradictory effects, and low doses of IL-10 potentiated LPS induced inflammation, while high IL-10 doses induced anti-inflammation." (PMID 30818819, 2019). "By contrast, interleukin 10 (IL-10) plays a protective role in a mouse experimental autoimmune uveoretinitis model and is upregulated in human uveitis patients." (PMID 30510488, 2018). "Our study demonstrates that rno-miR-30b-5p influences the development of uveitis by regulating the level of IL-10 and TLR4 positive cells, thereby playing a role in the pathogenesis of uveitis." (PMID 30510488, 2018). "The levels of IL-10 were lower in IOTB (1.89 ± 0.14) as compared to non-uveitis control group (3.42 ± 0.85, p = 0.007)." (PMID 30218032, 2018). "Our results indicate that rno-miR-30b-5p can influence on the pathogenesis of uveitis by regulating the expressions of IL-10 and TLR4." (PMID 30510488, 2018). "All these findings suggest that both TLR4 and IL-10 play a critical role in the pathogenesis of uveitis." (PMID 30510488, 2018). "We have previously reported that Th2 and Th17 cell-related cytokines; specifically IL-4, IL-10, IL-17A, IL-22, IL-31and TNFα, are exclusively elevated in the vitreous fluid of PDR compared with that of ERM, MH, or uveitis associated with sarcoidosis." (PMID 28558009, 2017). "In the process of the inflammatory reaction, immunoregulatory cytokines and growth factors, such as IL-10 and interferon-γ, play significant roles in eyes with uveitis." (PMID 26771310, 2016). "Although the mean level of IL-6 and IL-10 expression in uveitis vitreous samples differentiated them from tumor samples, overlapping was found in some cases." (PMID 23405064, 2013). "A review of medical records was completed, and aqueous levels of IL-10 and IL-6 from 10 patients with diffuse large B cell vitreoretinal lymphoma and 7 patients with uveitis are reported." (PMID 23750271, 2013).
uveitis (continued). "Before using the CBA multiplex technology to analyze the Th1/Th2 cytokine profiles of PIOL, OCL, and uveitis patients, we compared the IL-10 results produced by ELISA and CBA." (PMID 23405064, 2013). "Because IFNγ and IL-6 seemed to increase the IL-10 level of discrimination, we calculated IL-10/IL-6 and IL-10/IFNγ ratios to improve discrimination of PIOL/OCL versus uveitis patients." (PMID 23405064, 2013). "We demonstrated dynamic changes of the cytokine pattern during monophasic and relapsing-remitting disease with strongly increasing IL-10 expression in intraocular T cells during monophasic uveitis." (PMID 23155443, 2012). "In the eyes of R14-induced EAU we found significantly more IL-10+/IL-17+ cells than in eyes of PDSAg-induced uveitis at onset (p<0.05), while the opposite was observed during the resolution of disease (p<0.05)." (PMID 23155443, 2012). "There was only a minor population of IL-10+/IFN-γ+ cells (below 5%) in the eyes of R14-induced uveitis, which was stable during the course of disease." (PMID 23155443, 2012). "Regulatory T cells are expected to be responsible for preventing relapses of intraocular inflammation, and thus we have looked for Foxp3- and IL-10-expressing cells in the eyes and peripheral lymph nodes during monophasic and relapsing experimental uveitis." (PMID 23155443, 2012). "The effect of anti-TNF-α treatment in uveitis is explained by increasing the fraction of peripheral CD4+ T cells expressing IL-10 with a recovery of visual function." (PMID 21180427, 2010). "Increased levels of IL10+ T cells in aqueous humor compared with peripheral blood were also found in samples from patients with isolated uveitis but not those with associated systemic disease." (PMID 36715869, 2023). "Another study in 2008 demonstrated an intracameral injection of lentiviral-vector mediated expression of IL10 reduced inflammatory cell infiltrate and protein content in a mouse uveitis model suggesting that intraocular IL10 aids in maintaining integrity of the blood ocular barrier." (PMID 35980983, 2022). "The intraocular level of IL-10 reported in uveitis is still debatable." (PMID 35646978, 2022). "This type of uveitis is initiated by an early intraocular invasion of predominantly Th1 cells, while Th17 cells are increasing at the resolution of inflammation, probably playing an important role as regulatory cells, since they are co-expressing IL-10." (PMID 36325389, 2022). "Elevated IL-10 level was associated with uveitis, but lower or no different IL-10 expressions, were also documented in uveitis." (PMID 35646978, 2022). "We may summarize that the upregulation of inflammatory cytokines plays an important role in the pathophysiology of uveitis, mainly IL-6, as well as IL-1β, IL-2, INFγ, TNFα, IL-10, and GM-CSF." (PMID 33921773, 2021). "The coupled elevation of inhibitory cytokines IL-35 and IL-10 with IL-6 and IL-ll may represent an immunoregulatory response in uveitis." (PMID 33469457, 2020). "Furthermore, AAU patients displayed an elevated frequency of IL-10 and IL-4 expressing T cells during uveitis inactivity." (PMID 30105034, 2018). "Further bioinformatics analysis confirms that rno-miR-30b-5p can regulate the expressions of multiple target genes, including the immune-related inflammatory factors such as IL-10 and Toll-like receptors, and thus play an important role in the development and pathogenesis of uveitis." (PMID 30510488, 2018). "In addition, dexamethasone has been reported to down-regulate pro-inflammatory cytokines like INF-γ and TNF, while up-regulating the levels of IL-10 in peripheral blood mononuclear cells from uveitis patients." (PMID 26700298, 2015). "IL-6 was detected in 100% of the uveitis samples, IL-10 in 60%, and IFNγ in 48%." (PMID 23405064, 2013). "Nonetheless, some PIOL patients had low IL-10 levels and some uveitis patients high levels." (PMID 23405064, 2013).
uveitis (continued). "Finally, the graphic representation of the combination of the Logarithmic (Log10) conversion of IL-10/IL-6 and IL-10/IFNγ ratios helps to cluster the PIOL/OCL versus uveitis patients at diagnosis, with the upper right cluster specific for PIOL/OCL patients." (PMID 23405064, 2013). "We thus conclude that IL-10+ cells might be responsible for preventing relapses in PDSAg-induced uveitis, while the decreasing number of IL-10+ cells in the eyes of R14-induced uveitis might allow recurrent inflammation." (PMID 23155443, 2012). "The potential of IL-10 to suppress uveitis has been demonstrated by injecting a lentiviral-vector expressing IL-10 into the anterior chamber of the eye, by the protective effect of IL-10 injection during the afferent immune response of EAU and by a diminished uveitis in IL-10 transgenic mice." (PMID 23155443, 2012). "The intraocular levels of IL-10 and IL-12 in uveitis reported in the literature are controversial." (PMID 21850175, 2011). "None of the studied IL-17A or IL-10 polymorphisms seemed to mediate the risk of uveitis." (PMID 39125893, 2024). "However, authors hypothesized that EBV is not a direct cause of uveitis, but it may play a role as a secondary factor in the pathogenesis of uveitis, producing a homologue of IL-10." (PMID 30683065, 2019). "Thus, we infer that TLR4 may also stimulate the production of IL-10 in T lymphocytes and thus influencing the developing processes of uveitis." (PMID 30510488, 2018). "The network showed that LXD exerted therapeutic effects upon valuable targets participated in the genesis and development of uveitis, including Notch1, IL-6, IL-2, TNF, and IL-10." (PMID 40918405, 2025). "Aqueous humor cytokine analysis effectively distinguishes VRL from uveitis, with VRL patients exhibiting significantly higher IL-10 levels and an IL-10/IL-6 ratio >1.55, achieving 94.1% sensitivity and 100% specificity." (PMID 41403850, 2025). "SOCS1-KIR administration also led to significantly reduced TNFα and IL-10 secretion in PHA-stimulated equine PBMCs, isolated from both non-uveitis and ERU horses." (PMID 39867889, 2024). "The production of inflammatory cytokines induced by HTLV-1-infected T cells, such as IL-1α, IL-2, IL-3, IL-8, IL-10, TFN-α and GM-CSF, produces an intraocular inflammatory environment in patients with uveitis." (PMID 37605273, 2023). "Neutralization of IL-10 with antibody exacerbated EAU and overexpression of IL-10 in the eye ameliorated uveitis." (PMID 34054864, 2021). "rno-miRNA-30b-5p mimics can reduce the expression of IL-10 and TLR4 genes and proteins, thereby affecting the pathogenesis of uveitis." (PMID 32582189, 2020). "Increased intracellular IL-10 and IL-17A and decreased intracellular IFNγ levels were found in CD4+ T-cells from active uveitis, 6 months after starting treatment, when the disease had clinically resolved." (PMID 29774027, 2018). "It would be interesting to investigate how rno-miR-30b-5p regulates IL-10 and TLR4 and thus influence the pathogenesis of uveitis." (PMID 30510488, 2018). "This trend towards IL-10 production has already been observed in arthritic mice treated with dendrimer ABP and in a rat model of uveitis." (PMID 24745366, 2014). "The combination of the IL-10/IL-6 and IL-10/IFNγ ratios was highly informative for discriminating PIOL/OCL from uveitis samples and for therapeutic follow up of PIOL." (PMID 23405064, 2013). "In the second part of this work, we analyzed the Th1/Th2 cytokine profile, including IL-10, IL-6 and IFNγ, in vitreous and aqueous humor samples from patients with PIOL, oculocerebral lymphoma (OCL), uveitis, and retinal detachment (as controls)." (PMID 23405064, 2013). "IL-10 concentrations were next analyzed in the vitreous samples from PIOL, OCL, and uveitis patients." (PMID 23405064, 2013). "Despite the significant differences in the median IL-10/IL-6 and IL-10/IFNγ ratios between PIOL/OCL and uveitis samples, the range of values between these groups overlapped." (PMID 23405064, 2013).
uveitis (continued). "The combination of the IL-10/IL-6 and IL-10/IFNγ ratios was highly informative in its discrimination between PIOL/OCL and uveitis samples." (PMID 23405064, 2013). "The number of cells producing the suppressive cytokine IL-10 increased during the course of monophasic, PDSAg-specific EAU, while this population decreased during relapsing, R14-induced uveitis." (PMID 23155443, 2012). "In contrast, in eyes of R14-induced uveitis these populations were found at constant, very low levels (IFN-γ+/IL-10+) or even decreasing (IL-10+/IL-17+), allowing relapses of inflammation." (PMID 23155443, 2012). "During relapsing uveitis an increase of intraocular IFN-γ+ cells and a concomitant decrease of IL-17+ cells was detected, while IL-10+ populations remained stable." (PMID 23155443, 2012). "IL-10-producing cells accumulated in the eyes during monophasic disease, even populations producing IL-10 concomitantly with the inflammatory cytokines IFN-γ and IL-17 were dramatically increasing during the course of monophasic uveitis." (PMID 23155443, 2012). "Here, we show that the change of IL-10 mRNA expression and IL-6/IL-10 ratio during the first two weeks after CS therapy initiation can be used as biomarkers for refractoriness to CS treatment in uveitis patients independent of etiology of disease." (PMID 40433375, 2025). "Interestingly, IL-10 has been related to the disease onset and activity in SS, a disease that can present both DED and uveitis." (PMID 36715869, 2023). "IL-5, IL-10, and IL-13 showed 3-fold or more significant elevations in OT than in non-OT uveitis patients." (PMID 35646978, 2022). "Pairwise comparisons between IOL, ARN, and BE revealed that levels of IL-10 in IOL, RANTES (regulated on activation, normal T cell expressed and secreted) in ARN, and IL-22 in BE were significantly higher than those in the other 2 types of uveitis." (PMID 32066796, 2020). "An interesting finding is the decrease in IL-10 in the uveitis patients compared with controls, because IL-10 has not been observed to be involved in the generation or function of post-EAU Treg cells in mice." (PMID 31729418, 2019). "Therefore, we further explored the relationship between the expression levels of rno-miR-30b-5p and IL-10 and TLR4 and the development of uveitis." (PMID 30510488, 2018). "Rno-miR-30b-5p is downregulated in spleen, lymph nodes, and eye tissues in rats with experimental autoimmune uveitis, regulates the levels of IL-10 and TLR4, influences both IL-10 and TLR4 positive cell proportion within cell clusters, and thus suppresses the development of uveitis." (PMID 30510488, 2018). "It is well known that both IL-10 and TLR4 are involved in the development of uveitis." (PMID 30510488, 2018). "Similar to AAU patients, IAU patients displayed an elevated frequency of CD4+ IL-10+ T cells in comparison with HC, regardless of uveitis activity, and increased IL-4 expression during uveitis inactivity." (PMID 30105034, 2018). "Nevertheless, it is still unknown whether rno-miR-30b-5p regulates the expression of IL-10 and TLR 4 to influence the pathogenesis of uveitis." (PMID 30510488, 2018). "Vitreous samples from 60 patients with PIOL (n = 17), OCL (n = 9), uveitis (n = 23) or retinal detachment (RD) without hemorrhage (n = 11) were analyzed for IL-2, IL-4, IL-6, IL-10, IFNγ, and TNFα concentrations by CBA." (PMID 23405064, 2013). "Indeed, 48% (11/23) of the uveitis samples had an IL-6 concentration in the same range as PIOL/OCL samples and 38% (10/26) of the PIOL/OCL samples an IL-10 concentration in the same range as uveitis samples, consistent with a previous report." (PMID 23405064, 2013). "Lower intraocular levels of IL-8 and IL-10 were observed in AqH of children with uveitis treated with systemic methotrexate, but none of our patients used methotrexate at the time of sampling." (PMID 21850175, 2011).
uveitis (continued). "The exact functions of IL-10, IL-24, and TGF–β in relation to Th17 cells in EAU are ripe for further investigation, holding the promise of uncovering new therapeutic targets that could finely tune these cytokines to effectively manage uveitis." (PMID 40072803, 2025). "IL-10 was increased in infective uveitis compared with non-infective uveitis." (PMID 29673332, 2018). "Cytokines play a critical role in the pathogenesis of uveitis and we therefore investigated whether the different genotypes of rs2488457 affected production cytokines such as TNF-α, IL-1β, IL-6, IL-8, MCP-1, IFN-γ, IL-10 and IL-17." (PMID 24816862, 2014). "In our current study, we performed ELISA to assess the protein levels of IL-10, IL-6, IL-17A, and TNF-α in the serum of non-infectious uveitis patients." (PMID 40433375, 2025). "Results revealed that levels of IL-6, IL-10, TNF-α, FLT3l, PDGF-AB/BB, and sCD40L were significantly increased in both OT and non-OT uveitis patients, compared with the control group levels." (PMID 35646978, 2022). "The IL-10/IL-6 ratio, as previously reported, was slightly higher in PIOL than in uveitis samples, but not for all patients." (PMID 23405064, 2013). "Moreover, expression of IL-5, IL-9, IL-10, IL-13, and PDGF-AA, were significantly increased in the OT group alone, compared with the non-OT uveitis and control groups." (PMID 35646978, 2022). "However, percent detectable of IL-10, IL-31, IFN-γ, sCD40L, and TNFα, and mean vitreous levels of IL-6, IL-10, IL-31, IFN-γ, sCD40L, and TNFα were significantly higher in eyes with uveitis than in those with ERM or MH (data not shown)." (PMID 26352837, 2015). "In conclusion, the combination of the IL-10/IL-6 and IL-10/IFNγ ratios could be very helpful as an initial screening to rule out PIOL in uveitis patients." (PMID 23405064, 2013). "Though the level of equine-IL-10 transcript was not significant in the ciliary body of the low dose group, clinically this group effectively reduced EAU clinical symptoms, suggesting that even very low levels of AAV-Equine-IL10 may suppress uveitis symptoms." (PMID 35980983, 2022).